RAI14 (retinoic acid induced 14)
Diseases named in the same sentence as RAI14 in open-access papers (continued):
Sharing a sentence is not in itself a finding about the gene and the disease.
melanoma (continued). "To further confirm the effect of RAI14 knockdown on the expression of c-MYC in melanoma cells, we performed the Western blot and qPCR assays." (PMID 36233342, 2022). "MTT assays and plate clone assays showed that overexpression of RAI14 in knockdown melanoma cell lines restores cell proliferation." (PMID 36233342, 2022). "Eventually, rescue assays indicated that up-regulation of RAI14 observably counteracted the effects of AFAP1-AS1 suppression on melanoma cell proliferation, migration, invasion and EMT process." (PMID 32228518, 2020). "The TMOD3/RAI14/VWF axis interacts with the cytoskeleton in prostate cancer, and Liu and colleagues revealed that cell migration and the invasion of melanoma was impaired by RAI14 depletion via regulating the AFAP1-AS1/miR-653-5p/RAI14 axis." (PMID 32957082, 2020). "Eventually, rescue assays indicated that the function of AFAP1-AS1 in the cellular process of melanoma was dependent on miR-653-5p and RAI14." (PMID 32228518, 2020). "We also explored the subcellular localization of RAI14 in melanoma cells." (PMID 36233342, 2022). "We draw a model of the regulatory mechanism of RAI14 in melanoma." (PMID 36233342, 2022). "Interestingly, the expression of RAI14 was found to correlate with c-MYC signaling in melanoma by analyzing the R2 database." (PMID 36233342, 2022). "We found that the expression of RAI14 was higher in melanoma cell lines than in other cell lines." (PMID 36233342, 2022). "The expression of RAI14 can affect the proliferation, migration and invasion of melanoma cells." (PMID 36233342, 2022). "We also found that overexpression of RAI14 in melanoma cells reduced the turnover rate of c-MYC." (PMID 36233342, 2022). "Treatment of RAI14 knockdown melanoma cells with MG132 partly rescued c-MYC protein expression." (PMID 36233342, 2022). "Therefore, we used transwell and matrigel to explore the effect of RAI14 on melanoma cell migration and invasion." (PMID 36233342, 2022). "In summary, our data reveal an important role of RAI14 in melanoma development." (PMID 36233342, 2022). "We also found that the expression of RAI14 was significantly higher in melanoma than in nevus." (PMID 36233342, 2022). "However, the biological function of RAI14 in melanoma is unclear, and its molecular mechanism remains to be further explored." (PMID 36233342, 2022). "Taken together, these data suggest that RAI14 is essential for the growth of melanoma cells." (PMID 36233342, 2022). "In this study, RAI14 is highly expressed in melanoma and correlated with prognosis." (PMID 36233342, 2022). "In this study, we found that RAI14 can affect the expression of c-MYC in melanoma cells." (PMID 36233342, 2022). "RAI14 also has the structure of ankyrin repeat domain and coiled-coil domain; therefore, RAI14 may also function as a transcription factor or cofactor in melanoma." (PMID 36233342, 2022). "The results showed that knockdown of RAI14 could significantly inhibit the colony-forming ability of melanoma cells." (PMID 36233342, 2022). "Furthermore, transwell assay results indicated that overexpression of c-MYC restored cell migration ability of melanoma of the RAI14 knockdown group." (PMID 36233342, 2022). "To confirm whether RAI14 regulated melanoma progression by targeting c-MYC, we overexpressed c-MYC in RAI14 knockdown melanoma cells." (PMID 36233342, 2022). "We first explored the correlation between RAI14 and the prognosis of melanoma patients." (PMID 36233342, 2022). "Taken together, these data may suggest that RAI14 regulates melanoma progression by affecting c-MYC expression." (PMID 36233342, 2022). "The discovery of AFAP1-AS1/miR-653-5p/RAI14 axis may offer new insights into melanoma diagnosis and treatment." (PMID 32228518, 2020). "AFAP1-AS1 exerts its oncogenic function in melanoma by targeting miR-653-5p/RAI14 axis." (PMID 32228518, 2020).
melanoma (continued). "Therefore, it was safe to reach the conclusion that AFAP1-AS1 elicited cellular function changes of melanoma cells via targeting the miR-653-5p/RAI14 axis." (PMID 32228518, 2020). "Finally, all combined results uncovered that AFAP1-AS1 facilitates the malignancy of melanoma by targeting miR-653-5p/RAI14 axis." (PMID 32228518, 2020). "However, the biological function of RAI14 for the development of melanoma is unclear." (PMID 36233342, 2022). "In addition, restoring the expression of c-MYC could partially restore the proliferation and migration ability of melanoma cells in the RAI14 knockdown group." (PMID 36233342, 2022). "Besides, RAI14 was revealed to be markedly high-expressed in melanoma cells." (PMID 32228518, 2020). "To further confirm that RAI14 affects c-MYC ubiquitination through FBXO32, we knocked down the expression of FBXO32 in RAI14 knockdown melanoma cells." (PMID 36233342, 2022). "Therefore, we speculate that RAI14 may function as an oncogene in melanoma." (PMID 36233342, 2022). "However, the role of RAI14 in melanoma development remains unclear." (PMID 36233342, 2022).
triple-negative breast carcinoma (4 papers, 2022 to 2023). An invasive breast carcinoma which is negative for expression of estrogen receptor (ER), progesterone receptor (PR), and human epidermal growth factor receptor 2 (HER2). "Taken together, RAI14 is a reliable novel marker in the early diagnosis and chemotherapy monitoring of triple-negative breast cancer." (PMID 36880986, 2023). "STAMBP from the JAMM family stabilizes RAI14 protein by inhibiting K48 ubiquitination of RAI14 and promoting the development of triple-negative breast cancer." (PMID 37752518, 2023). "In this study, we aimed at determining the potential role of RAI14 in the early diagnosis and evaluation of chemotherapy efficacy in triple-negative breast cancer (TNBC)." (PMID 36880986, 2023). "CPN1 and RAI14 were expressed in triple-negative breast cancer cell lines and were positively correlated." (PMID 35431930, 2022). "Recent studies showed that RAI14 has a complementary effect to CA15-3 and a test combining the two parameters can improve the detection rate of early triple-negative breast cancer." (PMID 36880986, 2023).
esophageal cancer (3 papers, 2020 to 2023). A primary or metastatic malignant neoplasm involving the esophagus. "silencing of RAI14 inhibits the proliferation and invasion of BC cells and the progression of esophageal cancer (EC) through the STAT3 pathway." (PMID 36823639, 2023).
prostate carcinoma (3 papers, 2019 to 2022). A carcinoma that arises from epithelial cells of the prostate gland. "In prostate cancer, RAI14 involved in the regulation of tumor cytoskeletal cell compartments." (PMID 31772666, 2019).
cardiomyopathy (2 papers, 2022 to 2025). A disease of the heart muscle or myocardium proper. "The three genes under the greatest positive selection in the dN/dS analysis are implicated in either cardiomyopathy (RAI14, KIF6) or vasoregulation (PDE11A)." (PMID 35177770, 2022).
gastric tumors (2 papers, 2023 to 2024). "High expression of RAI14 in GC patients was associated with poor prognosis (Fig. EV1B), and RAI14 was highly expressed in gastric tumors compared to normal tissue (Fig. EV1C)." (PMID 39160347, 2024).
glioblastoma (2 papers, 2020). The most malignant astrocytic tumor (WHO grade IV). "RAI14 promotes mTOR-mediated inflammation under inflammatory stress and chemical hypoxia in U87 glioblastoma cell line." (PMID 32228518, 2020).
lung carcinoma (2 papers, 2017 to 2019). "In lung cancer, RAI14 was up-regulated in A549 and 31 of 71 patients." (PMID 31772666, 2019).
cognitive deficits (1 paper, 2022). "In this line, it is noteworthy that Rai14-deficient mice display a mild cognitive deficit and lower spine density, in that major depressive disorder is often associated with cognitive problems along with lower spine and synaptic densities." (PMID 35467532, 2022).
colon cancer (1 paper, 2023). "The effect of RAI14 silence on RKO cell migration was weaker than that in APC-mutated colon cancer cell lines DLD-1 and SW480." (PMID 36934880, 2023). "Of note, RAI14 was identified as a key prognostic indicator for APC-MUT colon cancer in both East Asians and Westerners, and high levels of RAI14 were linked to unfavorable prognosis." (PMID 36934880, 2023). "To reveal the roles of RAI14 in colon cancer, we knocked down RAI14 in the APC-mutated colon cancer cell lines DLD-1 and SW480 and overexpressed RAI14 in the SW480 cell line." (PMID 36934880, 2023). "Given that more than 50% of CRC patients have APC mutations, the prognostic utility of RAI14 in APC-MUT colon cancer may provide early warning and increase the chance of successful treatment." (PMID 36934880, 2023). "Due to the strong expression correlation between RAI14 and enzymes associated with RA biosynthesis in colon cancer, targeting the RA biosynthesis pathway to reduce the expression of RAI14 may be a promising therapeutic strategy for mAPC-II colon cancer patients." (PMID 36934880, 2023). "We find, for the first time, that RAI14 plays a decisive role in the prognosis of APC-MUT colon cancer." (PMID 36934880, 2023). "The prognostic utility of RAI14 in APC-mutant colon cancer will provide early warning and increase the chance of successful treatment." (PMID 36934880, 2023). "Here, we described the phenotypic heterogeneity of APC-mutant tumors and identified RAI14 as a key prognostic determinant for APC-mutant colon cancer patients." (PMID 36934880, 2023). "Collectively, these results indicate that RAI14 is an important variable determining the prognosis of APC-MUT colon cancer patients." (PMID 36934880, 2023). "Molecular subtyping of APC-MUT colon cancer identifies a combination of molecular markers predicting prognosis in APC-MUT tumors, in which high expression of RAI14 in tumors is associated with poor prognosis in both WCH and CPTAC cohorts." (PMID 36934880, 2023). "Collectively, this work describes the phenotypic heterogeneity of APC-mutant tumors and identifies RAI14 as an important prognostic determinant for APC-mutant colon cancer patients." (PMID 36934880, 2023). "Survival analysis of RAI14 showed that high expression of RAI14 was significantly correlated with unfavorable prognosis of colon cancer patients in the APC-MUT tumors but less significant in the APC-WT tumors (log-rank test, p = 0.013 for APC-MUT tumors and p = 0.066 for APC-WT tumors)." (PMID 36934880, 2023). "In addition, we found that colon cancer patients with high expression of RAI14 were less responsive to chemotherapy." (PMID 36934880, 2023). "Both transwell and scratch experiments showed that RAI14 knockdown dramatically inhibited cancer cell migration, while RAI14 overexpression reversed this phenotype, consistent with the poor prognosis of colon cancer patients with high levels of RAI14 in tumors." (PMID 36934880, 2023). "To explore the underlying mechanisms by which RAI14 affects the metastasis of colon cancer cells, we analyzed the proteomic and phosphoproteomic changes in DLD-1 cells after RAI14 knockdown, including two shRNAs and three repeats per shRNA." (PMID 36934880, 2023). "More importantly, we identified RAI14 as a key prognostic determinant for APC-mutant but not APC-wildtype colon cancer patients." (PMID 36934880, 2023). "Comparison between APC-MUT and APC-WT colon cancers suggested a nonspecific relationship between RAI14 expression and APC states, However, RAI14 exhibited more notable differences between the two subtypes in APC-MUT colon cancers than in APC-WT colon cancers." (PMID 36934880, 2023).
depression (1 paper, 2022). "As the gene expression analysis hints at the potential link between Rai14 deficiency and depressive disorder, Rai14+/- mice were tested in depression-like behavioral paradigms." (PMID 35467532, 2022). "At the same time, Rai14 deficiency resulted in the loss of dendritic spines, attenuation of synaptic function, and depression-like phenotypes, including behavioral deficits relevant to mood and cognition." (PMID 35467532, 2022). "This is intriguing because previous studies have reported the potential implications of Rai14 in the BDNF and mTOR pathways, which are critical processes for depression-associated synaptic remodeling." (PMID 35467532, 2022).
esophageal tumor (1 paper, 2022). "High expression of RAI14 may enhance the translocation of esophageal tumor cells." (PMID 36159818, 2022).
invasive ductal carcinoma (1 paper, 2022). "The expression of RAI14 is significantly different for invasive lobular carcinoma and invasive ductal carcinoma (p < 0.0001)." (PMID 35431930, 2022).
lymph node metastasis (1 paper, 2019). "Moreover, our clinicopathological data showed that RAI14 expression was significantly correlated to lymph node metastasis (p<0.001) and advanced TNM stages (p<0.001)." (PMID 31772666, 2019).
major depressive disorder (1 paper, 2022). An episode of depression lasting two or more weeks without an intervening episode of mania. "Among the significant gene sets enriched in Rai14+/- mouse brains, Aston-Major Depressive Disorder_DN (the set of downregulated genes in the temporal cortex samples from patients with major depressive disorder) showed a relatively high NES rank." (PMID 35467532, 2022). "(D) Heat map representation of transcripts included both in the ‘ASTON-Major depressive disorder_DN’ gene set and significant DEGs in Rai14+/- mouse brains." (PMID 35467532, 2022). "Indeed, among 18 genes that were included in both significant DEGs in Rai14+/- mouse brains and the Aston-Major Depressive Disorder_DN gene set, several genes were reported to be involved in dendritic spine regulation." (PMID 35467532, 2022). "The distribution of the gene set was significantly enriched in the downregulated genes of Rai14+/- group, and indeed, 17 genes out of 18 significant DEGs that are included in the Aston-Major Depressive Disorder DN gene set were downregulated in Rai14+/- mouse brain." (PMID 35467532, 2022).
mastitis (1 paper, 2021). Inflammation of breast tissue during lactation or postpartum due to an obstructed duct or infection. "RAI14 is located close to genomic regions associated with susceptibility of clinical mastitis in Holstein Friesian and milking speed in Scandinavian Holsteins." (PMID 33676402, 2021).
metastatic cancer (1 paper, 2022). A carcinoma which has spread from the original site of growth to another anatomic site. "Further understanding of STAMBP-dependent RAI14 protein stability may guide the development of improved strategies for the treatment of metastatic cancer, including TNBC." (PMID 36434041, 2022).
T-cell Lymphoma (1 paper, 2012). "Following the UCSC UMD3 assembly, candidate genes could be identified at or close to the peaks for regions #2 (TIAM1: T-cell Lymphoma Invasion and Metastasis 1), # 3 (GRIK1: Glutamate Receptor, Ionotropic, Kainate 1) and #4 (RAI14: Retinoic Acid Induced 14)." (PMID 22675421, 2012).
tumor (16 papers, 2016 to 2025). "RAI14 enhanced T cell-mediated anti-tumor responses by processing and presenting tumor-associated antigens to Th1 cells." (PMID 41361104, 2025). "These high RAI14 levels seem to be associated with tumor immune cell infiltration and indicate adverse outcomes for the patients." (PMID 36880986, 2023). "Nevertheless, the underlying functions and mechanisms of RAI14 regarding cancer progression and tumor immunology remain uncertain." (PMID 35431930, 2022). "Similar to the protumor effect of RAI14 in vitro, the overexpression of RAI14 reversed the xenograft tumor reduction caused by the knockdown of STAMBP to a certain extent." (PMID 36434041, 2022). "The utilization of high-throughput sequencing has enabled systematic investigations of genomic alterations in cancer, which have revealed the association between RAI14 and multiple tumor systems." (PMID 32957082, 2020). "The high expression of RAI14 in these malignant tumors is significantly associated with the drug resistance response of tumor drugs and the proliferation and invasion of tumor cells." (PMID 31772666, 2019). "It has been documented that a knockdown of the RAI14 gene can raise the sensitivity of tumor cells to drugs such as epi-amycin and cisplatin, and patients with high RAI14 expression are at higher risk of developing resistance to chemotherapeutic drugs (paclitaxel, epi-amycin, docetaxel, etc.)." (PMID 36880986, 2023). "Results showed that GAS7 expression was associated with inhibition of tumor metastasis (p = 3.906e−07), RAI14 expression was associated with high pathological grade (p = 0.036) and advanced clinical stage (p = 0.046), and SLC2A6 expression was associated with high pathological grade (p = 9.835e−04)." (PMID 33312950, 2020). "In addition, RAI14 is associated with tumor chemosensitivity." (PMID 36233342, 2022). "Animal studies revealed that Rai14-cKO accelerated tumor growth and reduced survival, but this effect was mitigated by Rnaseh2c-cKO." (PMID 41361104, 2025). "In tumor cells, RAI14 demonstrated a pro-tumorigenic effect, whereas in macrophages, it exhibited an anti-tumorigenic effect." (PMID 41361104, 2025). "The findings suggested that the tumor-regulatory function of RAI14 was contingent upon the specific cell type." (PMID 41361104, 2025). "The deletion of Rai14 in Hep-53.4 cells resulted in the suppression of subcutaneous tumor growth, whereas its overexpression produced the opposite effect." (PMID 41361104, 2025). "At the same time, RAI14 plays a more important role in chemotherapy monitoring than CA15-3 as the change in its concentration is in line with the tumor volume variation." (PMID 36880986, 2023). "After replacing the medication plan, the cancer cells were successfully killed, which resulted in a reduction of the tumor lesion and a notable decline in the RAI14 level." (PMID 36880986, 2023). "CRC single-cell transcriptome data show that in addition to being expressed in tumor cells, high levels of RAI14 are also observed in endothelial cells, fibroblasts, and myo-fibroblasts." (PMID 36934880, 2023). "RAI14 is significantly overexpressed in TNBC and is linked to adverse clinicopathological features such as tumor burden, CA15-3 levels and the ER, PR, and HER2 status of the patients." (PMID 36880986, 2023). "The changes in tumor size, RAI14, and CA15-3 levels in parallel to the chemotherapy cycles in the other four patients were analyzed in a comprehensive manner." (PMID 36880986, 2023). "miR-653-5p was identified to target different genes, such as EMSY, and RAI14, which participate in many tumor developments." (PMID 34983591, 2022). "The relationship of RAI14 expression on tumor-infiltrating immune cell markers in the different molecular subtypes was analyzed using the TIMER database." (PMID 35431930, 2022). "To investigate the effect of RAI14 on tumor growth, we explored the effect of RAI14 on tumor cell self-renewal by soft agar assay." (PMID 36233342, 2022).